CD24 (CD24 molecule)
Diseases named in the same sentence as CD24 in open-access papers (continued):
Sharing a sentence is not in itself a finding about the gene and the disease.
gastric adenocarcinoma (9 papers, 2012 to 2024). "Our data demonstrate the presence of a subset of cells with a CD24+CD44+CD54+EpCAM+ phenotype in gastric adenocarcinomas from 127 patients." (PMID 36737794, 2023). "A pattern of CD44+ high/CD24+ low expression is a cardinal character of cancer stem cell activity in gastric adenocarcinoma." (PMID 33233485, 2020). "Further, CD24 mediates gastric adenocarcinoma cell survival and invasion by activating STAT3 signaling and regulating extracellular matrix protein and VDR expression." (PMID 29772698, 2018). "It was found that CD24 expression was not different in intestinal-type and diffuse-type of gastric adenocarcinoma." (PMID 25503963, 2014). "CD44 and CD24 expression levels were investigated immunohistochemically in tumor samples from 290 patients with non-cardia gastric adenocarcinoma, of whom 77 had paired adjacent normal gastric mucosa." (PMID 25212506, 2014).
nasopharyngeal carcinoma (9 papers, 2003 to 2025). A carcinoma arising from the nasopharyngeal epithelium. "We found that nasopharyngeal carcinoma (NPC) cells with high expression of CD44 and CD24 proteins presented with pronounced CSC properties." (PMID 27521216, 2016). "Researchers have attempted to isolate nasopharyngeal carcinoma (NPC) CSCs through side population, and specific biomarkers, such as CD44, and CD24." (PMID 27521216, 2016). "To investigate the involvement of stem cells in Epstein-Barr virus infection-related nasopharyngeal carcinoma (NPC), we used double immunofluorescence staining to examine several cancer stem/progenitor cell markers (CD44v6, CD24, and ALDH1A1) in NPC tissues and NPC cell lines." (PMID 27647953, 2016). "Stable knockdown of Wnt5a in S18 nasopharyngeal carcinoma cells significantly decreased the percentage of CD24−/CD44+ stem-like cells, while over-expression of Wnt5a in S26 nasopharyngeal carcinoma cells S26 significantly increased the percentage of CD24−/CD44+ cells." (PMID 27571105, 2016).
non-small cell lung carcinoma (9 papers, 2013 to 2024). A group of at least three distinct histological types of lung cancer, including non-small cell squamous cell carcinoma, adenocarcinoma, and large cell carcinoma. "In addition, expression of ITGβ4, CD24 and Notch were shown to confer non-small cell lung carcinoma (NSCLC) propagation in clonogenic and othotoptic transplantation assays." (PMID 33800889, 2021). "For example, after radiotherapy, resistant cells display a complex phenotype involving a combination of the properties of CSCs and EMT with higher expression of Snail, CD44, CD24, and PDGFR-β (platelet derived growth factor receptor β) in non-small cell lung cancer (NSCLC) cells." (PMID 28872613, 2017).
periodontitis (9 papers, 2009 to 2026). An acute or chronic inflammatory process that affects the tissues that surround and support the teeth. "On the other hand, increased titers of serum antibodies to CD24 have been correlated with less severe periodontitis, suggesting a protective role of CD24 on the gingivae." (PMID 29390019, 2018). "CD24 is selectively strongly expressed by the epithelial attachment to the tooth and by the epithelium lining of the lesion of chronic periodontitis." (PMID 19138432, 2009). "An increase in inflammatory cytokines has been hypothesized to elevate the expression of CD24, which could be the case in severe periodontitis." (PMID 40351293, 2025). "Studies have shown that CD24 is selectively expressed in epithelial cells of the dental attached gingivae, and increased reactivity of CD24 can be observed in the epithelium lining the gingival pockets produced by chronic periodontitis." (PMID 29390019, 2018). "The consistent high expression of CD24 has been reported in the epithelial attachment to the tooth and in the migrating epithelium of the periodontitis lesion, and titres of serum antibodies auto-reactive with CD24 peptide correlates with the remission of periodontal disease." (PMID 26705104, 2015). "As subjects with mild chronic periodontitis have increased titres of serum antibodies auto-reactive with CD24 compared with those of subjects with severe periodontitis, a molecular mechanism for regulated expression of the NLRP3 inflammasome mediated by c-Src kinase activity, is proposed." (PMID 25866631, 2014). "Peripheral blood from 55 patients with stage 2 periodontitis and 20 healthy controls was analyzed using flow cytometry to evaluate the frequency of CD19+CD24+CD38+ Breg cells." (PMID 32604936, 2020). "In the present study, CD19+, CD24+, and CD38+ were used as markers to characterize Breg cells from peripheral blood of periodontitis patients." (PMID 32604936, 2020). "CD24, EST1, MTSS1, ING3, CCND2 and SYNE2 may have the potential to be used as targets for periodontitis diagnosis and treatment.; however, more research is still needed to validate our findings." (PMID 26705104, 2015).
acute respiratory distress syndrome (8 papers, 2020 to 2025). Progressive and life-threatening pulmonary distress in the absence of an underlying pulmonary condition, usually following major trauma or surgery. "Remarkably, CD24-Fc also lowered the incidence of pneumonia and protected against acute respiratory distress syndrome (ARDS) in these NHPs." (PMID 39763958, 2024).
cervical cancer (8 papers, 2011 to 2025). A primary or metastatic malignant neoplasm involving the cervix. "Consistent with previous studies in cervical cancer, CD24 overexpression was preferentially associated with poor survival (p = 0.025)." (PMID 41354057, 2025). "From this perspective, combining M1‐polarized macrophage infiltration and CD24/CD47 expression is more effective than CD24/CD47 alone in classifying cervical cancer patients." (PMID 41354057, 2025). "Demographic and histopathologic characteristics of cervical cancer patients with different CD24 or CD47 expression levels." (PMID 41354057, 2025). "It was also observed that CD24 promoted the proliferation and invasion of cervical cancer cells in vitro, inhibited their apoptosis, and helped cervical cancer cells to develop radiotherapy resistance." (PMID 40486886, 2025). "This study explored the association between CD24/CD47 expression and macrophage infiltration and clinical outcomes in cervical cancer." (PMID 41354057, 2025). "Accordingly, the protein expression level of CD24/CD47 in cervical cancer was significantly higher than that of normal cervical tissue." (PMID 41354057, 2025). "This study is the first report investigating dual CD47 and CD24 expressions and comparing their correlation with clinicopathologic and prognostic characteristics in cervical cancer." (PMID 41354057, 2025). "Our study implies that high CD24 expression is an important predictor of a worse prognosis, and CD24 blockade might have therapeutic potential for the treatment of cervical cancer." (PMID 41354057, 2025). "The expression level of CD24 is an independent prognostic factor for cervical cancer." (PMID 41354057, 2025). "Concerning the relationship between CD24 expression and the EMT features, heterogeneity of cervical cancer cells has been recently reported: only cells having CD44 (+) CD24 (-) phenotype exhibited mesenchymal traits and attained invasive, migratory and spreading abilities." (PMID 32899940, 2020). "In contrast to CD24, which exhibits prognostic implications for cervical cancer irrespective of its association with CD11c, the prognostic value of CD47 is contingent on CD11c, particularly the abundance of infiltrating macrophages within the cervical cancer microenvironment." (PMID 41354057, 2025). "Our results provide evidence for the therapeutic potential of CD24 and CD47 blockade, with particular promise for the treatment of cervical cancer." (PMID 41354057, 2025). "To investigate the prognostic potential of CD24 and CD47, we performed survival analysis for 264 cervical cancer cases whose survival data and sequencing results were obtained from OncoLnc." (PMID 41354057, 2025). "Study shows among the radiation-resistant cervical cancer cells, most are CD44+/CD24+ cells, which share other CSC characteristics, such as B lymphocytoma 2 (Bcl-2), increased expression of survival proteins, and show greater tumorigenicity." (PMID 40486886, 2025). "In this study, we integrated CD24 and CD47 into the analysis of cervical cancer from TCGA and Fudan University Shanghai Cancer Center (FUSCC)." (PMID 41354057, 2025). "The current study was performed to examine the therapeutic potential of CD24 and CD47 blockade in cervical cancer." (PMID 41354057, 2025). "Patients with high CD24 expression had poorer survival than those with low CD24 expression in the TCGA and FUSCC cervical cancer cohorts." (PMID 41354057, 2025). "The expression of CD24 and CD47 was detected by immunohistochemistry in tissue microarrays composed of 130 clinical cervical cancer specimens from Fudan University Shanghai Cancer Center (FUSCC)." (PMID 41354057, 2025). "The study provides potential prognostic markers and increases the feasibility of CD24 and CD47 blockade in cervical cancer treatment." (PMID 41354057, 2025).
cervical cancer (continued). "The expression of markers of the immune system such as CD95, MICA/B, CD39, CD73, NKp30, NKp46, CD44, CD24, NKG2A, and CTLA-4 was analysed by flow cytometry on cervical cancer cells INBL (HPV 18, stage IVB), HeLa (HPV 18), CaSki (HPV 16), and C33A (HPV-)." (PMID 31198791, 2019). "CD24 gene expression was higher in cervical cancer samples compared to neighboring non-cancerous tissues." (PMID 40486886, 2025).
endometrial cancer (8 papers, 2013 to 2025). Primary or metastatic malignant neoplasm involving the endometrium (mucous membrane that lines the endometrial cavity). "We report on the evaluation of 3 antigens—human epidermal growth factor receptor 2 (HER2), mucin-16 (MUC16), and CD24—as potential radiotheranostic targets in endometrial cancer." (PMID 40841152, 2025). "Herein, we describe the exploration of 3 biomarkers—human epidermal growth factor receptor 2 (HER2), mucin-16 (MUC16), and CD24—as potential radiotheranostic targets for endometrial cancer." (PMID 40841152, 2025). "Radiopharmaceutical therapy represents a third possibility for the application of HER2- and CD24-targeted radioimmunoconjugates in endometrial cancer." (PMID 40841152, 2025). "PERTINENT FINDINGS: HER2 and CD24 are abundantly expressed in endometrial cancer cells as well as patient-derived tissue samples representing several molecular subtypes of the disease, while the expression of MUC16 is more sparing and variable." (PMID 40841152, 2025). "This investigation illustrated the potential of HER2 and CD24 as radiotheranostic targets in endometrial cancer." (PMID 40841152, 2025). "For example, in endometrial cancer, ARTN specifically regulates CD24 to stimulate endometrial cancer cell resistance to doxorubicin and paclitaxel." (PMID 34496868, 2021). "In endometrial cancer cell lines, CD24 promotes the expression of ATP‐binding cassette (ABC) transporters via the Met signaling cascade, ultimately leading to cancer drug resistance." (PMID 32394616, 2020). "CD24, for example, has been found expressed in a cyclic pattern in the normal endometrium and endometrial carcinoma." (PMID 23468957, 2013). "IMPLICATIONS FOR PATIENT CARE: HER2- and CD24-targeted immuno-PET could prove valuable in the clinic as a theranostic tool to identify patients with endometrial cancer who are likely to respond to HER2- and CD24-targeted therapeutics." (PMID 40841152, 2025). "QUESTION: Are HER2, MUC16, and CD24 promising radiotheranostic targets in endometrial cancer?" (PMID 40841152, 2025). "The clear potential of HER2 and CD24 as molecular targets in endometrial cancer raises the question of how these 2 targets could be exploited for clinical nuclear medicine." (PMID 40841152, 2025). "Similarly, CD24 recruits p‐Met to the lipid raft domain, resulting in the drug resistance of endometrial cancer." (PMID 32394616, 2020). "In addition, experiments are under way to explore the utility of [89Zr]Zr-DFO-trastuzumab and [89Zr]Zr-DFO-ATG-031 as companion theranostics in endometrial cancer alongside HER2-targeted antibody–drug conjugates and CD24-targeted immunotherapeutics." (PMID 40841152, 2025). "Furthermore, CD24 may play a role in chemotherapy resistance in triple‐negative breast cancer (TNBC), HCC, and endometrial cancer, further implicating it as a potential drug target." (PMID 32394616, 2020).
lymphoma (8 papers, 2016 to 2025). A malignant (clonal) proliferation of B- lymphocytes or T- lymphocytes which involves the lymph nodes, bone marrow and/or extranodal sites. "Accordingly, CD24 is used as a cellular marker of progression for this lymphoma as it is used for other tumors associated with poor prognosis." (PMID 28360912, 2017). "CD24‐high DLBCL seems to be skewed to the ‘effacement’ pattern because immune cells are less than in CD24‐low lymphoma." (PMID 35289116, 2022). "As CD24‐expressing lymphoma had a poor prognosis in all three datasets examined, we next examined the characteristics of CD24‐expressed lymphomas." (PMID 35289116, 2022). "The expression of CD24 on LBC lymphoma correlates with the early stage of T-cell differentiation when the neoplastic transformation of the tumor cells took place." (PMID 28360912, 2017). "We found that all of the lymphoma samples consistently expressed B220, CD24, CD38, CD43, CD93, and CD138." (PMID 26740101, 2016). "Moreover, the number of double‐hit lymphomas was higher in the CD24‐high group than in the CD24‐low group (p < 0.001)." (PMID 35289116, 2022). "CD24 expression was also higher in single‐hit lymphoma than in DLBCL, NOS (p = 0.002)." (PMID 35289116, 2022). "Therefore, we asked whether CD24 expression on lymphoma cells alters the immune microenvironment to explore immune cell‐specific gene expression in DLBCL." (PMID 35289116, 2022). "Of note, certain types of NHLs such as mantle cell lymphoma (MCL) or follicular lymphoma (FL), retained CD24 expression in contrast to healthy counterparts, with MCL being a more aggressive lymphoma that comprises about 3% to 10% of total NHL cases." (PMID 35625912, 2022). "CD24 expression was higher in BL than in DLBCL including double‐hit lymphoma, lymphoma with single hit of the MYC gene, and DLBCL, NOS in Hummel's dataset (GSE4475)." (PMID 35289116, 2022). "We next examined the number of non‐lymphoma TME cells including macrophages and M2 macrophages, CD3‐positive T‐cells, and CD8‐positive cytotoxic cells between CD24‐high and CD24‐low groups." (PMID 35289116, 2022). "Although significantly lower levels of CD20+CD27+CD24+CD40+CXCR4+CXCR5+ B cells were observed in MC14 of HIV+ pre-NHL (cART-naïve) samples, these cells had a potential pre-lymphoma phenotype as they expressed both cMYC and AICDA compared to HIV+ cART-naïve and HIV-negative samples." (PMID 39324141, 2024). "Apart from the results of the analyses of the GEPs, the expression of CD24 did not correlate with the frequency of double‐hit lymphoma (p = 0.053) or MYC rearrangement (p = 0.2)." (PMID 35289116, 2022). "The prognosis was worse in patients with high CD24 expression than in those with low CD24 expression, both in double‐hit lymphoma and in the group without MYC rearrangement." (PMID 35289116, 2022). "As international prognostic index (IPI) and COO significantly predict OS, multivariable analysis of prognosis showed that CD24 was the only gene associated with a worse OS independent of the IPI and COO of the lymphoma, with P‐value less than 0.05." (PMID 35289116, 2022). "In patients treated with an agent targeting CD22, CD24 may serve to identify normal and neoplastic B cells; however, not all cases of B-lymphoblastic leukemia/lymphoma are CD24 positive, so analysis for additional B cell markers, such as CD79a, may be helpful." (PMID 40227608, 2025). "B-lymphoblastic leukemia/lymphoma with KMT2A rearrangement typically has a CD19-positive, CD10-negative, CD24-negative, and TdT-negative immunophenotype, as well as positivity for myeloid markers CD15 and CD65." (PMID 40227608, 2025). "Unlike CD24, mRNA expression levels of CD47 were similarly high in all lymphomas." (PMID 35625912, 2022).
pancreatic adenocarcinoma (8 papers, 2011 to 2021). "Dual treatment of pancreatic adenocarcinoma cells with anti-CD24 mAb and cetuximab enhanced phagocytosis relative to either treatment alone, demonstrating a potential synergy between anti-CD24 mAb and anti-solid-tumor mAbs." (PMID 32765491, 2020). "Statistical analysis showed that the coexpression of ANXA10 and CD24 was highly correlated with the progression of pancreatic adenocarcinoma through low- to high-grade PanINs." (PMID 28369074, 2017). "In their study, human Colo357 pancreatic adenocarcinoma cells were treated in vitro with anti-CD24 mABs, which resulted in the arrest of cell growth in a dose- and time-dependent manner, while the cells negative to CD24 expression were not similarly affected." (PMID 26394139, 2015). "CD24 expression was found in 76.6% (49/64) of pancreatic adenocarcinomas." (PMID 28369074, 2017). "Together with the result that CD24 plays an important role in stimulating tumor cell proliferation, the coexpression of ANXA10 with CD24 indicates that ANXA10 may be involved in the early event during the development of pancreatic adenocarcinoma." (PMID 28369074, 2017). "In this study, we sorted CD44+CD24+ESA+ CSCs in pancreatic adenocarcinoma cell line PANC-1." (PMID 24521357, 2014). "The co-localization of ANXA10 and CD24 in PDACs and high-grade neoplasia lesions suggests that these two markers may play roles in regulating the progression of pancreatic diseases and the development of pancreatic adenocarcinoma." (PMID 28369074, 2017). "Flow cytometric analysis was used to determine the presence of CD44, CD24 and ESA on the cell surface of the pancreatic adenocarcinoma cell lines PANC-1." (PMID 24521357, 2014). "Recently, CSCs from pancreatic adenocarcinoma based on ALDH activity and the expression of the CD44 and CD24, and CD133 have been identified." (PMID 21304978, 2011). "The expression patterns of the stem cell surface markers CD44, CD24 and ESA in pancreatic adenocarcinoma cell lines are diverse and not all CSCs sorted from pancreatic adenocarcinoma cell lines develop cell spheres, PANC-1 is a common pancreatic adenocarcinoma cell line used for study of CSCs." (PMID 24521357, 2014). "Although ALDH expression was not examined in this study, co-expression of CD44 and CD24 was observed in ∼0.1% of CD133+ CSCs, again suggesting the possibility that multiple, distinct tumor-initiating populations exist in pancreatic adenocarcinoma." (PMID 21695188, 2011).
psoriasis (8 papers, 2012 to 2026). An autoimmune condition characterized by red, well-delineated plaques with silvery scales that are usually on the extensor surfaces and scalp. "Next, we calculated the AUC values of ECGs in the 15 non‐tumour diseases, finding that ECGs had the highest diagnostic value for burns, with CD24 achieving an AUC of 0.99 in the diagnosis of psoriasis." (PMID 40576208, 2025). "CD19(+)CD27(+)CD24(high) Breg cells exhibit reduced expression in psoriasis and psoriatic arthritis patients, correlating inversely with Psoriasis Area and Severity Index (PASI) scores." (PMID 38596682, 2024). "Our data imply that certain B-cell panels, such as CD20−AC, unsw mem %lymphocyte, CD20− %lymphocyte, CD20 on IgD+ CD38−, CD27 on IgD+ CD24+, CD27 on IgD− CD38br, CD27 on IgD− CD38dim, CD38 on naive-mature B cell, and IgD on IgD+ CD38−unsw mem, are related to an elevated risk of psoriasis." (PMID 38558803, 2024). "We demonstrate a similar staining pattern of psoriasis and CD24 in DCIS in vivo." (PMID 23300877, 2012). "The ROC curves demonstrated that the expression levels of eight Hub Genes—POSTN, CD274, CD24, SERPINB3, CXCL13, SMPD3, BIRC5, and RAB27A—exhibited high accuracy (AUC > 0.9) in classifying the Psoriasis and Control groups." (PMID 40557155, 2025).